ZNF679 (zinc finger protein 679)
Description:
May be involved in transcriptional regulation.
Synonyms: MGC42415
Tractability: PROTAC: ubiquitination databases record sites on it.
Gene: Protein-coding gene on chromosome 7 (64,228,474 to 64,266,931, forward strand). Ensembl gene ENSG00000197123.
Subcellular location: Nucleus
Pathways (Reactome):
Gene expression (Transcription): Generic Transcription Pathway
Gene Ontology:
Molecular function: protein binding; DNA-binding transcription factor activity, RNA polymerase II-specific; RNA polymerase II cis-regulatory region sequence-specific DNA binding
Biological process: regulation of DNA-templated transcription; regulation of transcription by RNA polymerase II
Cellular component: nucleus
Genetic constraint (gnomAD): Loss-of-function variants: 10 observed, 12.29 expected, observed/expected ratio (o/e) 0.81, 90% interval 0.5 to 1.38. The upper end of that interval is the gene's LOEUF score, 1.38, which puts it in group 5 of 6, group 1 being the genes least tolerant of losing a copy. Missense variants: 512 observed, 471.74 expected, observed/expected ratio (o/e) 1.09, 90% interval 1.01 to 1.17. Synonymous variants: 169 observed, 162.48 expected, observed/expected ratio (o/e) 1.04, 90% interval 0.92 to 1.18.
Homologues: Orthologues: chimpanzee ZNF679 (98% identical), macaque ZNF679 (91% identical). Paralogues in human: ZNF716 (82% identical), ZNF735 (82% identical), ZNF722 (78% identical), ZNF254 (69% identical), ZNF728 (68% identical), ZNF708 (67% identical), ZNF726 (67% identical), ZNF506 (64% identical), ZNF486 (63% identical), ZNF90 (63% identical), ZNF714 (62% identical), ZNF676 (61% identical), and 164 more.